RET (ret proto-oncogene)
Diseases named in the same sentence as RET in open-access papers (continued):
Sharing a sentence is not in itself a finding about the gene and the disease.
neurodevelopmental disorder (2 papers, 2017 to 2023). A behavioral and cognitive disorder with onset during the developmental period that involves impaired or aberrant development of intellectual, motor, or social functions. "Moreover, RET and NRG1 double mutation zebrafish embryos showed the most severe neurodevelopmental disorders compared to single mutation and control sibling embryos." (PMID 37484916, 2023).
connective tissue disorder (1 paper, 2024). A disease involving the connective tissue. "Due to the patient history of multiple vascular abnormalities and the suspicion of a possible genetic connective tissue disorder, comprehensive genetic testing with whole exome sequencing was performed, identifying a heterozygous pathogenic variant in RET (c.2410G>T p.{Val804Leu})." (PMID 39512978, 2024). "Although no connection to a connective tissue disorder was identified, a heterozygous pathogenic variant NM_020975.6:c.2410G>T p.(Val804Leu) in exon 14 of RET gene was detected." (PMID 39512978, 2024).
gastrointestinal disease (1 paper, 2010). A disease that occurs in the gastrointestinal system, excluding the hepatobiliary system. "The RET gene is the major gene implicated in this gastrointestinal disease." (PMID 20532249, 2010).
respiratory disease (1 paper, 2020). "GFRα2, RET, and MMP2 mRNA expression was analysed in lung macrophages from patients with COPD compared with patients with no underlying respiratory disease." (PMID 33020210, 2020).
RET also shares sentences with these, for which no sentence is quoted: multiple endocrine neoplasia type 1 (8 papers); brain tumors (6); familial isolated hyperparathyroidism (6); hereditary cancer-predisposing syndrome (5); neuroma (5); Noonan syndrome (5); tuberous sclerosis (5); achondroplasia (4); clear cell renal cell carcinoma (4); colon adenoma (4); colorectal adenocarcinoma (4); Costello syndrome (4); fibrosarcoma (4); Hypercalcemia (4); hypothyroidism (4); pancreatic ductal carcinomas (4); soft tissue sarcoma (4); Alzheimer disease (3); basal cell nevus syndromes (3); C-cell hyperplasia (3); diabetes (3); endometrial cancer (3); esophageal cancer (3); ganglioneuroma (3); head and neck paraganglioma (3); Hyperparathyroidism-jaw tumor syndrome (3); invasive breast carcinoma (3); Marfan syndrome (3); Merkel-cell carcinomas (3); mucosal (3).
A further 221 diseases each share a sentence with RET in 3 papers or fewer.